FGF23 (fibroblast growth factor 23)
Diseases named in the same sentence as FGF23 in open-access papers (continued):
Sharing a sentence is not in itself a finding about the gene and the disease.
left ventricular hypertrophy (continued). "Elevated serum concentrations of FGF23 were associated with increased mortality as well as other adverse health outcomes, e.g., progression in left ventricular hypertrophy and renal disease." (PMID 29602956, 2019). "High plasma FGF-23 levels are associated independently with endothelial dysfunction, arterial stiffness, left ventricular hypertrophy, progression of renal disease, and mortality and cardiovascular events." (PMID 31035488, 2019). "Circulatory FGF23 levels have been shown to be associated with various adverse events such as higher mortality, cardiovascular events, and left ventricular hypertrophy, especially in subjects with CKD." (PMID 29515522, 2018). "FGF23 is also linked to iron metabolism, erythropoiesis, inflammation, insulin resistance, proteinuria, and left ventricular hypertrophy." (PMID 30197987, 2018). "Adverse events associated with high FGF23 are quite diverse including cardiovascular events, left ventricular hypertrophy, progression of CKD, fractures, higher mortality, frailty, insulin resistance, and so on." (PMID 29515522, 2018). "Several studies in populations with preserved renal function and early CKD have linked FGF-23 to left ventricular hypertrophy and decreased left ventricular ejection fraction." (PMID 29850246, 2018). "In a breakthrough discovery, Faul and colleagues showed a causal function of FGF23 in the pathogenesis of left ventricular hypertrophy." (PMID 28974056, 2017). "Elevated FGF23 in patients with CKD has been shown to be a risk factor for left ventricular hypertrophy and cardiovascular events, progressive loss of kidney function, and death." (PMID 29186198, 2017). "High FGF23 levels are associated with increased mortality and left ventricular hypertrophy in dialysis patients." (PMID 25112372, 2014). "During the past decade, reports of clinical studies have described the association between FGF23 and cardiovascular risks, left ventricular hypertrophy, and vascular calcification." (PMID 24678415, 2014). "High FGF-23 plasma levels are independently associated with endothelial dysfunction, arterial stiffness, left ventricular hypertrophy, progression of renal disease, incidence of mortality and cardiovascular events." (PMID 24748388, 2014). "In our previous analyses, we found that FGF23 is associated with left ventricular hypertrophy and cardiac systolic dysfunction." (PMID 25200959, 2014). "FGF-23 concentrations increase with kidney failure and elevated FGF-23 has been associated with abnormal endothelial function, adverse cardiovascular outcomes, and has recently shown to cause left ventricular hypertrophy." (PMID 24646518, 2014). "In line, several clinical studies associated FGF-23 with markers of myocardial damage, namely left ventricular hypertrophy and left ventricular dysfunction." (PMID 25528363, 2014). "Recent studies have shown that high levels of FGF23 are associated with poor outcomes such as left ventricular hypertrophy, progression of CKD and increased overall mortality." (PMID 23705925, 2013). "This possibility is indirectly supported by the observation that higher FGF-23 levels are associated with vascular calcification, endothelial dysfunction and left ventricular hypertrophy in CKD patients." (PMID 23526964, 2013). "Recent studies have shown an association between circulating FGF23 levels and pathologic cardiovascular conditions, including left ventricular hypertrophy, and vascular endothelial dysfunction." (PMID 24039882, 2013). "FGF23 is also an independent risk factor for left ventricular hypertrophy and cardiovascular disease in the general population." (PMID 22970174, 2012). "Elevated FGF23 levels are associated with left-ventricular hypertrophy and hypertension in patients with X-linked hypophosphatemia (XLH)." (PMID 22970174, 2012). "The possible association of FGF-23 and left ventricular hypertrophy or vascular dysfunction has been proposed." (PMID 21234310, 2010).
left ventricular hypertrophy (continued). "It has recently been reported that FGF-23 is independently associated with left ventricular hypertrophy in patients with CKD." (PMID 21234310, 2010). "A plethora of clinical studies have shown that elevated circulating levels of the phosphaturic fibroblast growth factor 23 (FGF23) are associated with left ventricular hypertrophy (LVH), atrial fibrillation, systolic and diastolic dysfunction, as well as heart failure." (PMID 41152461, 2025). "Linked to FGF23 excess, left ventricular hypertrophy is a common and serious complication of CKD." (PMID 40773297, 2025). "Furthermore, the FGF23 association with cardiovascular pathologies, such as left ventricular hypertrophy and atherosclerosis, underscores its potential as a biomarker for assessing cardiovascular risk." (PMID 38732094, 2024). "For example, in the heart, FGF23 might cause left ventricular hypertrophy in a klotho‐independent manner via FGFR4." (PMID 38050660, 2024). "It showed an association between elevated FGF-23 and left ventricular hypertrophy." (PMID 37298029, 2023). "Although the underline mechanism has not been elucidated, it is suggested that exogenous erythropoietin generated by ESAs can largely increase C-terminal fibroblast growth factor 23 (FGF23) level, which is significantly associated with left ventricular hypertrophy and an increased risk of mortality." (PMID 35445052, 2022). "FGF23, a hormone for regulation of phosphate hemostasis and the renin–angiotensin–aldosterone system, is an indicator of both renal and myocardial dysfunction and is associated with left ventricular hypertrophy and clinical outcomes." (PMID 33439866, 2021). "FGF23 is associated with left ventricular hypertrophy (LVH) in CKD and induces LVH via klotho-independent FGFR4-mediated activation of calcineurin/nuclear factor of activated T cells (NFAT) signaling in animal models, displaying systemic alterations possibly contributing to heart injury." (PMID 34778257, 2021). "Alternatively, this finding could also be explained by FGF-23’s potential impact on the heart to promote left ventricular hypertrophy, which in turn may increase the risk of stroke and cerebrovascular induced cognitive impairment." (PMID 33306729, 2020). "In addition, elevated levels of circulating FGF23 have been associated with left ventricular hypertrophy (LVH), and it has been suggested that FGF23 directly affects the myocardium." (PMID 32235720, 2020). "In addition, increased FGF23 levels have also been associated with vascular calcification and left ventricular hypertrophy." (PMID 30830941, 2019). "Moreover, elevated circulating FGF-23 are independently associated with vascular dysfunction, left ventricular hypertrophy, and death." (PMID 31185930, 2019). "Whilst circulating FGF-23 levels rise rapidly during AKI and a causal role for FGF-23 in the pathogenesis of left ventricular hypertrophy has previously been unveiled, suggesting that chronically elevated FGF-23 levels contribute directly to cardiac mortality in patients with CKD." (PMID 30082648, 2018). "It is well documented that higher FGF23 levels are associated with increased arterial stiffness, total body atherosclerosis, left ventricular hypertrophy, and consequently, there is an increased risk cardiovascular mortality, even in patients without renal insufficiency." (PMID 28977159, 2017). "Several study have reported that both elevated FGF23 and vitamin D deficiency may cause left ventricular hypertrophy via activation of the calcineurin pathway and the renin-angiotensin-aldosterone system, respectively." (PMID 28747700, 2017). "Thus, even in middle-aged and older adults with preserved kidney function, subclinical left ventricular hypertrophy may enhance cardiomyocyte-derived FGF23 production, potentially causing mild elevations in circulating FGF23 levels." (PMID 41038963, 2025).
left ventricular hypertrophy (continued). "Animal studies have shown that FGF23 can induce left ventricular hypertrophy (LVH) through FGFR4, and in patients higher FGF23 levels predispose to development of LVH." (PMID 40237064, 2025). "We and others have recently shown that circulating fibroblast growth factor-23 (FGF23) levels are increased in murine MI and left ventricular hypertrophy models." (PMID 41515999, 2025). "Vice versa, angiotensin II administration to Hyp mice led to an increase in FGF23 levels, blood pressure and left ventricular hypertrophy." (PMID 40152980, 2025). "Low klotho levels are associated with increased oxidative stress, inflammation, and accelerated aging-like phenotypes, while elevated FGF-23 independently predicts left ventricular hypertrophy and mortality in CKD patients." (PMID 40002748, 2025). "FGF23 has previously been shown to have a direct role in cardiac dysfunction mediated through left ventricular hypertrophy." (PMID 40464156, 2025). "Of interest, FGFR4 inhibitors are currently being developed and tested in cancer, opening potential for downstream targeting of high FGF23 levels in CKD patients to prevent the development of left ventricular hypertrophy and heart failure [63,64▪▪]." (PMID 40237064, 2025). "In line with this, FGF23, locally produced in the failing heart, induces left ventricular hypertrophy." (PMID 40483378, 2025). "It has also been suggested FGF-23 can promote the progression of left ventricular hypertrophy by inducing pro-hypertrophic genes directly through autocrine pathways." (PMID 41151250, 2025). "In late-stage CKD, FGF-23 cannot reduce serum phosphate levels, and high FGF-23 concentrations result in left ventricular hypertrophy (LVH), faster CKD progression, and mortality." (PMID 38919625, 2024). "Although the impact of FGF23 on bone health in children is yet to be determined, FGF23 is known to have several “off-target” effects on cardiac myocytes with an increased prevalence of left ventricular hypertrophy." (PMID 38347283, 2024). "This FGF23-mediated disruption of cardiac tissue and the subsequent left ventricular hypertrophy establish one of the many forms of the cardiorenal syndrome." (PMID 38792638, 2024). "Previous studies revealed that elevated levels of FGF23 induce left ventricular hypertrophy in mice through FGFR4." (PMID 38560469, 2024). "The proposed mechanism is that elevated serum levels of FGF23 lead to left ventricular hypertrophy and endothelial dysfunction, worsening arterial stiffness, and accelerated cardiovascular damage in patients with CKD24–29." (PMID 37949967, 2023). "Hyperphosphatemia leads to a depletion of Klotho levels and increased FGF-23 levels, both of which directly contribute to left-ventricular hypertrophy followed by cardiac fibrosis and coronary calcification." (PMID 38255650, 2023). "In the same study, intramyocardial or intravenous application of FGF-23 resulted in left-ventricular hypertrophy in mice." (PMID 37749114, 2023). "Accumulating recent clinical evidence suggests that FGF-23 plays a regulatory role in multiple pathological processes in cardiovascular diseases, such as coronary atherosclerosis, vascular calcification, left ventricular hypertrophy, and myocardial injury." (PMID 37089720, 2023). "Several studies have reported that increased FGF-23 levels are associated with CKD progression, left ventricular hypertrophy, and premature death." (PMID 36873652, 2023). "The hormonal effects of circulating klotho protein and FGF23 on the vascular and heart have contributed to arterial stiffness and left ventricular hypertrophy." (PMID 37334749, 2023). "High circulating levels of FGF-23 directly contribute to left ventricular hypertrophy (LVH) and anemia in patients with CKD." (PMID 35602513, 2022).
left ventricular hypertrophy (continued). "In pediatric CKD cohorts, higher circulating concentrations of fibroblast growth factor 23 (FGF23) are associated with some of these adverse clinical outcomes, including CKD progression and left ventricular hypertrophy." (PMID 35237863, 2022). "The prevalence of left ventricular hypertrophy and vascular calcification was higher in the low Klotho/FGF23 ratio quartiles at baseline and at the fourth-year follow-up." (PMID 35872753, 2022). "There is increasing evidence of pathological effects of dysregulated FGF23 levels, such as induction of left ventricular hypertrophy, cardiac fibrosis, and dysfunction, and FGF23 is therefore discussed as a risk factor and biomarker for cardiovascular disease." (PMID 35958252, 2022). "Two elegant experimental studies have proved that FGF23 can directly induce left ventricular hypertrophy in vivo and in vitro." (PMID 35801203, 2022). "Compared with the CHD group, the INHD group presented with a significantly reduced circulating iFGF23 level, which was closely associated with attenuation of left ventricular hypertrophy, but INHD reduced all-cause mortality in an FGF23 independent manner." (PMID 35801203, 2022). "It was demonstrated that the cause of left ventricular hypertrophy in CKD is early and prolonged induction of fibroblast growth factor 23 (FGF23)." (PMID 36140195, 2022). "One study reported that elevated FGF-23 exhibited increased blood pressure and left ventricular hypertrophy in angiotensin II treated animals." (PMID 35604403, 2022). "Estimated direct and mediated effects of FGF23 on left ventricular hypertrophy (LVH) for each of the renin-angiotensin-aldosterone system (RAAS) parameters of interest." (PMID 35559350, 2022). "Together with elevated FGF23 levels this can result in left ventricular hypertrophy and ultimately heart failure, which is most exaggerated in patients on hemodialysis and contributes substantially to cardiovascular mortality in CKD." (PMID 34994388, 2022). "Calcimimetic therapy is effective in lowering serum concentrations of fibroblast growth factor 23 (FGF23), which is a risk factor for left ventricular hypertrophy (LVH) and cardiovascular events in people with CKD." (PMID 35872799, 2022). "At 23 weeks, Col4a3KO mice showed impaired kidney function, increased levels of kidney and serum LCN2, increased bone and serum FGF23, anemia, and left ventricular hypertrophy (LVH)." (PMID 34334787, 2021). "Several studies have illustrated correlations between high FGF23 levels and numerous deleterious effects, including left ventricular hypertrophy, vascular calcification, and mortality." (PMID 34678981, 2021). "Laboratory evidence indicated that FGF-23 directly induces left ventricular hypertrophy through the activation of the FGF receptor." (PMID 35008591, 2021). "Preclinical studies demonstrated that FGF23 can lead to left ventricular hypertrophy in cardiac myocytes, and promote endothelial dysfunction." (PMID 32512806, 2020). "Left ventricular hypertrophy (LVH) is an important contributor to cardiovascular morbidity in patients with CKD and LVH is associated with high FGF23 concentration." (PMID 32130720, 2020). "Some of the proposed mechanisms include a possible direct cytotoxic effect of excess FGF23 on the myocardium leading to left ventricular hypertrophy and arterial calcification through phosphorus and vitamin D regulation." (PMID 31107896, 2019). "Preclinical studies demonstrated that FGF23 can induce left ventricular hypertrophy by binding to FGF23 receptor 4 in cardiac myocytes, and promote endothelial dysfunction." (PMID 31170159, 2019). "Clinical studies in CKD patients showed a correlation of elevated FGF23 levels to left ventricular hypertrophy (LVH)." (PMID 31540546, 2019).
left ventricular hypertrophy (continued). "Particularly, increased FGF-23 levels in patients with CKD are clinically relevant to CV mortality by inducing left ventricular hypertrophy, arterial stiffness combined with endothelial dysfunction, and vascular calcification." (PMID 31892319, 2019). "The phosphaturic hormone FGF23 is essential for the regulation of phosphate levels in CKD patients, but excessive FGF23 levels are also associated with left ventricular hypertrophy (LVH), cardiac fibrosis, and hypertension." (PMID 31698866, 2019). "Higher FGF23 levels are related to pathogenesis of left ventricular hypertrophy and inflammation in CKD." (PMID 31615432, 2019). "Elevated levels of FGF-23 are associated with an increased cardiovascular risk in patients with CKD, and with left ventricular hypertrophy in a cohort of CKD patients." (PMID 31551803, 2019). "Elevated circulating FGF23 was shown to induce left ventricular hypertrophy (LVH) via the calcineurin/NFAT pathway and contributed to cardiac fibrosis by stimulation of profibrotic factors." (PMID 31540546, 2019). "A high concentration of FGF23 is related to a worsening of the prognosis and deterioration of left ventricular hypertrophy in patients with CKD." (PMID 29518087, 2018). "The calcineurin-nuclear factor of activated T cells signaling pathway is involved in FGF23-induced left ventricular hypertrophy in an animal model." (PMID 29518087, 2018). "Increased FGF-23 levels in both CKD and general populations are associated with left ventricular hypertrophy, congestive heart failure, atrial fibrillation, and mortality." (PMID 29850246, 2018). "For example, elevated FGF23 has been shown to directly induce left ventricular hypertrophy in mice, which supports observations of greater left ventricular mass with higher levels of FGF23 in patients with CKD." (PMID 30249044, 2018). "In patients with CKD, FGF-23 supraphysiologic levels were strongly associated with LVMI, left ventricular hypertrophy (LVH), cardiovascular events, and mortality." (PMID 30462803, 2018). "In conclusion, we have shown for the first time that slightly increased FGF23 concentrations in early stages of CKD induced disturbed calcium fluxes in cardiomyocytes that are independent from left ventricular hypertrophy and global cardiac dysfunction." (PMID 29611320, 2018). "As an example, the steep and early increase of the bone-derived phosphaturic FGF-23 keeps serum phosphate well within the normal range and at the same time triggers left ventricular hypertrophy and cardiovascular disease in CKD patients." (PMID 28570715, 2017). "Studies have indicated a connection between circulating FGF23 levels and cardiovascular pathologies such as left ventricular hypertrophy." (PMID 28974056, 2017). "The enhanced myocardial expression of FGF23 strongly correlates with the presence of left ventricular hypertrophy (LVH)." (PMID 27803896, 2016). "Other studies have shown a strong correlation between FGF-23 levels and left ventricular hypertrophy (LVH) in patients with CKD." (PMID 27805564, 2016). "Serum FGF23 levels, which are elevated with the progression of CKD, are associated with left ventricular hypertrophy (LVH), a major contributor to cardiovascular disease (Jimbo and Shimosawa, 2014; Wyatt and Drüeke, 2016)." (PMID 27803896, 2016). "A potential longer term effect of concern is that higher levels of FGF23 are associated with both cardiovascular events and death in advanced CKD and that FGF23 is associated with left ventricular hypertrophy (LVH) in human studies." (PMID 27852236, 2016). "FGF23 induces hypertrophic growth of cardiac myocytes in rodents and promotes left ventricular hypertrophy by activating FGF receptor-4, and left ventricular hypertrophy is an independent risk factor for heart failure." (PMID 27495287, 2016). "Regarding the cardiovascular system, FGF-23 has been shown to induce left ventricular hypertrophy, vascular calcification, arterial stiffness and endothelial dysfunction." (PMID 26024521, 2015).